SULF2 (sulfatase 2)
Diseases named in the same sentence as SULF2 in open-access papers (continued):
Sharing a sentence is not in itself a finding about the gene and the disease.
tumor (continued). "Despite similar substrate specificity, SULF1 has mainly tumor suppressor functions whereas SULF2 presents tumor promoting functions." (PMID 21599997, 2011). "In this article, we focused on recent and challenging data describing the implication of SULF1 and SULF2 in human neoplasia." (PMID 21599997, 2011). "A number of reports demonstrated that over-expression of Sulf-1 or Sulf-2 in tumor cell lines inhibited growth factor signaling in response to several factors, including FGF-2, HB-EGF, and HGF." (PMID 17460759, 2007). "Proteomic analysis confirmed the absence of SULF1 in the knockout cell cultures and revealed that SULF2, expressed in tumor cells, does not compensate for its loss." (PMID 41549062, 2026). "In addition, the precise reasons for the different properties of SULF1 and SULF2, one a tumor suppressor in many biological contexts and the other an established oncogene, need to be determined." (PMID 40140347, 2025). "We tested the ability of the MO-I-1151 ASPH inhibitor alone or in combination with a recently described SULF2 inhibitor HfFucCS with regard to the invasion of HNSCC tumor cells in a spheroid co-culture model with a primary HNSCC cancer-associated fibroblast (CAF 61137)." (PMID 38732216, 2024). "We used the model to establish the ability of the ASPH inhibitor MO-I-1151 to inhibit the invasion of HNSCC tumor cells into Matrigel, and we showed an additive inhibitory effect of its combination with a recently described heparan 6-O-endosulfatase (SULF2) inhibitor, HfFucCS." (PMID 38732216, 2024). "Importantly, targeting SULF2 protein with a monoclonal antibody abolishes tumour growth in a mouse CCA xenograft model." (PMID 38332153, 2024). "Additionally, IHC results of subcutaneous tumor tissues showed that in contrast to the oe-SULF2 group, the expression of SULF2 and proliferation marker Ki67 was significantly reduced in the sh-SULF2 group." (PMID 36612128, 2022). "Moreover, in vivo and in vitro experiments revealed that SULF2 promotes tumor proliferation and invasion." (PMID 36612128, 2022). "Elevated SULF2 expression in CAFs demonstrated no specific associations with tumour grade or stage, but survival was similarly reduced in the presence of CAFs-SULF2 upregulation (12.2 months vs. 35.0 months)." (PMID 36589727, 2022). "In addition, we saw a significant downregulation of SULF2 protein in tumor tissues of HBV-related HCC (log2FC = −0.33, FDR < 0.001) and UCEC (log2FC = −0.43, FDR = 0.01)." (PMID 36428645, 2022). "Finally, our RNAScope study shows that SULF1+ cells localize to the stroma while SULF2+ cells overlap to a large degree with the cytokeratin+ tumor cells." (PMID 36428645, 2022). "In carcinomas, SULF-1 and SULF-2 are usually downregulated and overexpressed, respectively, but their expression may change depending on tumor stage and the hypoxia level in the tumor microenvironment (TME)." (PMID 36359323, 2022). "To investigate whether SULF2 mediates the formation of lung metastatic tumor nodules in vivo, we measured SULF2 mRNA levels in lung tissues using qRT-PCR." (PMID 34440158, 2021). "On the other hand, it has been found that the family of heparin-degrading endosulfatases involving SULF1 and SULF2 were implicated in the pathophysiology of numerous cancers, including HCC with an opposing action either as a tumor suppressor action with SULF1 or as an oncogenic action with SULF2." (PMID 33076548, 2020). "However, we did not observe the expected decrease of the 6-O-sulfated disaccharides in the SULF2+ve tumor tissues." (PMID 33585200, 2020). "Consequently, SULF2 siRNA inhibited the growth of xenograft tumors, with a significant decrease in tumor weight." (PMID 32049100, 2020). "Thus, the decreased Ki67 expression in the nude mice treated with SULF2 siRNA suggested that SULF2 siRNA limited the proliferation and growth of xenograft tumor cells in vivo." (PMID 32049100, 2020).
tumor (continued). "Several other genes synthesizing the HS chains are upregulated in tumor tissues, and groups of the genes (e.g. EXT1, EXT2, and SULF2) may be jointly regulated in the tumor tissues." (PMID 33585200, 2020). "Therefore, modification of the glycocalyx (HSPG in particular) in the tumor microenvironment by Sulf1, Sulf2, or heparanase affects cancer cell proliferation, signaling, invasion, and metastasis." (PMID 30135409, 2018). "However, the roles of Sulf1 and Sulf2 in different types of tumor growth under different microenvironments are ambiguous." (PMID 30135409, 2018). "Similarly to heparanase, the two extracellular endosulfatases, Sulf-1 and Sulf-2, were found to be dysregulated in a wide range of human malignancies where they affect the tumor microenvironment and cell signaling by modifying the structure and function of HS." (PMID 30413079, 2018). "In cancer biology Sulf1 is thought to act as a tumour repressor but Sulf2 as a tumour enhancer." (PMID 27535874, 2017). "To investigate whether SULF2 contributes to IR-induced tumor metastasis, we irradiated tumors in mice with sublethal doses of IR." (PMID 26895473, 2016). "Importantly, this function of SULF2 appears to also operate in vivo, as we further demonstrated that sublethal doses of IR increased SULF2 expression in tumor cells in mice and also promoted their intravasation in a SULF2-dependent manner." (PMID 26895473, 2016). "However, such a generalisation appears to be misleading because there is evidence that in some instances Sulf-1 promotes, while Sulf-2 inhibits, tumour growth." (PMID 27408707, 2016). "Moreover, studies using cancer cells and animal models have shown that SULF2 can facilitate tumor growth and migration, supporting its role in tumor formation and progression." (PMID 26895473, 2016). "The HNSCC tumor tissues showed significantly higher SULF2 staining in all the scored categories." (PMID 27223083, 2016). "Importantly, this effect of IR was prevented by expressing SULF2 shRNA in tumor cells, supporting the possibility that SULF2 mediates the ability of IR to promote cancer cell invasion in vivo." (PMID 26895473, 2016). "SULF2 staining was positive for 82% of the samples (Either tumor or stroma staining)." (PMID 26882224, 2016). "It is of interest to note that as intimated in the PDAC setting, the tumor type, the Sulf isoform (Sulf1 and/or Sulf2), and the predominant pathway (Wnt or FGF2) might result in opposing effects of Sulf’s on tumor progression and metastasis." (PMID 25105093, 2014). "This section highlights some of the prevalent cancer types, which have reported significant alterations in heparanase, Sulf1, and/or Sulf2 and how these changes in expression correlate with indices of cancer progression such as prognostic indicators, tumor development, metastasis, and survival." (PMID 25105093, 2014). "Apart from the opposing roles played by Sulf1 and Sulf2 in regulating tumor growth through mobilizing heparan binding growth factors, these endosulfatases are also involved in regulating apoptotic proteins enhancing the sensitivity to chemotherapeutic agents in ovarian cancer." (PMID 25105093, 2014). "The reason why SULF2 unmethylation increases tumor sensitivity to cisplatin may lie on ubiquitin conjugating enzymes (UBE)." (PMID 24124496, 2013). "However, if heparanase is clearly associated to protumorigenic effects, contradictory observations have been made concerning SULF1 and SULF2 contribution in human neoplasia, as we have discussed in this article." (PMID 21599997, 2011). "The upregulation of Sulf-2 raises the possibility that it may be involved in promoting tumor progression." (PMID 16417632, 2006).
tumor (continued). "Thus, Sulf-2 interaction with LG3BP may regulate the physiological activity of the Sulf-2 enzyme as well as its activity in the tumor microenvironment." (PMID 38825040, 2024). "Interestingly, the mean expression of SULF1 in SULF1-positive cells remains significantly higher in fibroblasts than in tumor cells (2.291 vs. 1.232, p < 0.001); however, the mean expression of SULF2 in SULF2-positive fibroblasts and tumor cells is the same (1.826 vs. 1.812, p = 0.8)." (PMID 36428645, 2022). "Therefore, SULF2 is highly expressed in BCa and increases IL-8 secretion, which promotes the polarization of macrophages to the M2-type and enhances the malignant progression of the tumor through the communication between BCa cells and macrophages." (PMID 36612128, 2022). "We did not observe an association between SULF2 mRNA expression and tumor stage." (PMID 33585200, 2020). "EXT1, EXT2, and SULF2 are probably co-upregulated in tumor tissues according to the correlation analysis and higher gene expression in SULF2-positive tumors than in SULF2-negative tumors, but the mechanism underlying such upregulation still needs to be further explored." (PMID 33585200, 2020). "Therefore, the slight decrease in tumor size caused by SULF2 shRNA did not appear to significantly influence the number of circulating tumor cells." (PMID 26895473, 2016). "Our results show a significant association between increased SULF2 distribution and intensity in tumor tissue and cancer stage; SULF2 increases from early (stage 1 and 2) to advanced (stage 3 and 4) tumors approximately 2-fold, suggesting that SULF2 may be involved in cancer progression." (PMID 27223083, 2016). "Expression analysis revealed a positive correlation between LINC00313 and TCF7, SULF2 and AXIN2 mRNA levels in resected tumours." (PMID 38332153, 2024). "We have shown previously that the marine fucosylated chondroitin sulfate HfFucCS, a newly identified inhibitor of heparan 6-O-endosulfatase SULF2, is an inhibitor of HNSCC tumor cell invasion." (PMID 38732216, 2024). "In contrast, SULF2 expression in the PDX increases (median primary tumor TPM = 50, median PDX TPM = 103, p < 0.01; Wilcoxon rank-sum test) which confirms that the tumor cell is the major source of this enzyme." (PMID 36428645, 2022). "In summary, SULF2 expression increases in multiple malignancies but less consistently than SULF1, which uniformly increases in the tumor tissues and negatively impacts survival in several types of cancer even though its expression in cancer cells is low." (PMID 36428645, 2022). "An increase in extracellular sulfatase (SULF1 and SULF2) in human GBM regulates important interactions of growth factors and ECM components to PGs, thus mediating tumor cell invasion and proliferation." (PMID 35202840, 2022). "The percentage of positive cells among individual patients ranges from 2.4–54.5% for SULF1 and 43.1–91.7% for SULF2 in tumor cells, and from 31.3–71.0% for SULF1 and 8.7–43.8% for SULF2 in fibroblasts." (PMID 36428645, 2022). "Nuclear RelA-P-ser536 in tumour cells and the presence of CAF-SULF2 were strongly correlated (Spearman's rho 0.722; p < 0.0001, Pearson χ2 test 0.005), supporting stromal SULF2 as a regulator of a RelA-P-ser536 in human HCC in vivo." (PMID 36589727, 2022). "We conclude that SULF1 and SULF2 in HNSC derive primarily from the fibroblasts and tumor cells, respectively." (PMID 36428645, 2022). "The largely podocyte-specific transcription factor Wilms’ tumor gene 1 (WT1) regulates the expression of SULF2 and SULF1, and children with this tumor exhibited a kidney phenotype similar to that in SULF2 and SULF1 knock-out mice." (PMID 33540508, 2021). "Our previous research revealed that Sulf2 can stimulate the expression and secretion of POSTN through TGFβ1 in the HCC tumour microenvironment." (PMID 34193219, 2021).
tumor (continued). "Both heparanase and Sulf2 are capable of increasing expression of HSPG targeted to the cell surface and, consequently, increasing pro-tumor signaling by HS-binding growth factors." (PMID 25105093, 2014). "In contrast, Sulf1 has been found to be downregulated in a number of cancer types while Sulf2 is typically overexpressed in carcinomas but importantly, these may be differentially expressed depending on the stage of cancer and the level of hypoxia in the tumor microenvironment." (PMID 25105093, 2014). "Although Sulf2 is purported to exhibit an oncogenic effect in HCC, in contrast, Sulf1 has been identified as having a tumor suppressor effect in HCC." (PMID 25105093, 2014). "Heparanase, Sulf1, and Sulf2 have been shown, by virtue of their enzymatic modification of the ECM, to affect the signaling of a number of proteins that are important drivers of tumor growth or progression." (PMID 25105093, 2014). "The identified genes are involved in drug transport and detoxification (ABCB1, DNAJC15, GSTP1, RAB6C), DNA damage repair (BRCA1) as well as tumor cell proliferation/invasion (APC, CDH1, ESR1, HIC, PLAU, RASSF1, SULF2, TGM2)." (PMID 20544021, 2010). "Moreover, we measured increased SULF2 and AXIN2 expression in LINC00313 xenograft tumours, compared to control." (PMID 38332153, 2024). "SULF2 not only changes the function of HSPG by regulating 6-O-sulfation but also plays an important role in the occurrence and development of tumors, such as participating in the tumor cell cycle, proliferation, apoptosis, and other biological functions." (PMID 36612128, 2022). "In a 2D transwell culture, COS-7 cells increased the metabolic activity and cellular proliferation of both Huh7 and Hep3B cells, while tumour cells alone or co-cultured with SULF2 KD COS-7 cells did not (online suppl." (PMID 36589727, 2022). "SULF2 mRNA expression is significantly higher in tumor tissues that demonstrated strong staining for SULF2 protein compared to tumors negative for SULF2 staining." (PMID 33585200, 2020). "We found that SULF2 mRNA is detectable in the tumor tissues negative by SULF2 IHC, which suggests that the production of SULF2 protein is regulated by some post-transcriptional mechanisms in addition to the mRNA expression." (PMID 33585200, 2020). "In addition, SOD2 mediated cell invasion induced by extracellular factors, such as IL-6 and SULF2, suggesting that SOD2 plays an essential role in cell invasion induced in response to tumor microenvironment changes." (PMID 30755594, 2019). "Tumor expression of SULF2 may affect prognosis in NSCLC, while blood SULF2 levels may have a significant role in the diagnosis of this fatal disease." (PMID 26882224, 2016). "The number of circulating tumor cells was not significantly altered by the expression of SULF2 shRNA." (PMID 26895473, 2016). "The tumor location had no statistically significant (p value > 0.05) effect on the intensity of SULF2 expression or the proportion of cells that showed staining in the four sites tested." (PMID 27223083, 2016). "Another mechanism, recently discovered, by which heparanase is able to promote tumor malignancy is via the stimulation of exosome secretion, although as yet Sulf1 and Sulf2 have not been shown to be involved in this process." (PMID 25105093, 2014). "Rather than having uniformly tumor-promoting properties, Sulf1 and Sulf2 have pro- and anti-tumor affects." (PMID 25105093, 2014). "SULF2 is oncogene,it promotes the release of growth and angiogenic factors such as FGF-I, FGF −2, VEGF and DSF –I by mobilizing heparin-bound growth factors, leading to increased tumor growth and a more rapid rate of tumor recurrence after surgery." (PMID 24359226, 2013). "The different stages refer to tumor size, but the pattern between tumor size and SULF2 expression is not clear because stage 2B’s SULF2 expression is lower than the lesser tumor stage 2A’s SULF2 expression; whereas, the higher stage 3B had the highest SULF2 expression." (PMID 40140347, 2025).
tumor (continued). "Nuclear RelA-P-ser536 positivity was scant/absent in tumour cells in the absence of SULF2." (PMID 36589727, 2022). "It is also known as protein kinase B (PKB) play an important role in angiogenesis in pathological condition and tumor growth via different Ser/Thr kinase family members like liver kinase B1 (LKB1), calcium/calmodulin-dependent protein kinase IV (CAMKIV), and sulfatase (SULF2)." (PMID 34754365, 2021). "D0A0 is slightly higher in SULF2+ve tumor but this trend is not significant." (PMID 33585200, 2020). "It is plausible to speculate that reduced 6-O-sulfation in tumor compared to adjacent normal tissues is not resulted from the single event of SULF2 overexpression but the dysregulated biosynthetic pathway of heparan sulfate chains." (PMID 33585200, 2020). "In addition, the weight of the tumors in the SULF2 siRNA group (206.65±20.16 mg) was reduced compared to those in the control group (532.26±51.76 mg) (P<0.05), while no obvious changes in tumor volume and weight were observed between the control and NC groups (all P>0.05)." (PMID 32049100, 2020). "This indicates that the Sulf‐2 in the cocultures did not compensate for the lack of Sulf‐1, which further supports the importance of Sulf‐1 provided by CAF in the tumor microenvironment." (PMID 41549062, 2026). "Stromal CM induced activation of JNK and STAT3 pathways in the tumour cells in the presence and absence of SULF2, with JNK inhibition suppressing both SULF2-dependent and independent Hep3B spheroids growth." (PMID 36589727, 2022). "Besides the wide-scale overexpression in tumor tissues, SULF1 is significantly downregulated in KICH and THCA and SULF2 in PRAD but none of the studies reaches a 2-fold decrease." (PMID 36428645, 2022). "However, SULF1 and SULF2 mRNAs are >20-fold higher in the PDAC tumor tissues than in the non-disease pancreatic tissue from the GTEx (SULF1 log2FC = 6.81, SULF2 log2FC = 4.85, both p < 0.001), which is consistent with the large difference in the protein expression." (PMID 36428645, 2022).